MSN (moesin)
Diseases named in the same sentence as MSN in open-access papers (continued):
Sharing a sentence is not in itself a finding about the gene and the disease.
breast carcinoma (continued). "Pre-incubation of T47-D or MCF-7 breast cancer cells with the specific Rho-kinase inhibitor, Y-27632 (Y-27632, 10 μM) prevented the activation of moesin by estradiol, implying that ROCK-2 is required for estrogen signaling to moesin in ER+ breast cancer cells." (PMID 18493596, 2008). "The role of moesin in keeping HER2 in a repressed status may provide novel treatment approaches by targeting moesin for HER2-positive breast cancer." (PMID 39457653, 2024). "Moesin participates in regulation of breast cancer therapeutic resistance." (PMID 37740172, 2023). "Interestingly, it was shown that AKT kinase, a highly activated oncogenic kinase in breast cancer, phosphorylates both Moesin and SKP2 to activate their oncogenic potential." (PMID 37736741, 2023). "Third, the hormonal status of breast cancer may affect the significance of the ENO1/MSN-Mtdh regulatory axis in response to lymphocyte-derived iTSC CM." (PMID 36923539, 2023). "Furthermore, moesin plays an important role in the EMT process of breast cancer cells and pancreatic cancer cells, and is currently shown to serve as a potential EMT marker for breast cancer and pancreatic cancer." (PMID 37179366, 2023). "Further, it was found that Moesin is highly expressed in hormone receptor positive as well as negative breast cancer patients and its high-level expression is closely associated with poor prognosis." (PMID 37736741, 2023). "In contrast, FBXW2 is under expressed in all the breast cancer cell lines tested compared to the normal cell line indicating that ablation of FBXW2 might be responsible for accumulation of Moesin in breast cancer cells." (PMID 37736741, 2023). "TMEM16A and ROCK1/moesin signaling cooperatively promotes breast cancer metastasis." (PMID 35668455, 2022). "Estrogen hormone binding to either of its receptors, estrogen receptor α and β (ERα and β), through extranuclear signaling can drive actin cytoskeleton modification, cancer cell migration, invasion, and metastasis via phosphorylation of moesin in ER-positive breast cancer cells." (PMID 34689178, 2022). "The result indicates that MSN's interaction with CD44 may contribute to repressing breast cancer stem cells." (PMID 34976221, 2022). "The observed moesin-mediated inhibition of CD44 signaling may contribute to removing breast cancer stem cells." (PMID 34976221, 2022). "Interestingly, gene silencing of moesin greatly reduces the plasma membrane localization of PD-L1 in a human breast cancer cell line, implying a novel role of moesin in modulating the protein expression levels of PD-L1 via post-translational modification." (PMID 34577564, 2021). "Interestingly, gene silencing of moesin dramatically decreased the plasma membrane localization of PD-L1 in human breast cancer cell lines, indicating a novel regulatory mechanism of PD-L1 by ERM family proteins via post-translational modifications." (PMID 34681187, 2021). "Our study suggested that CD44 cross-linking could elevate p-Moesin expression and further affect migration and invasion of breast cancer cells." (PMID 33292278, 2020). "The expressions of ERM complex in a panel of breast cancer cell lines indicate that Moesin and its phosphorylation may play a significant role in cell metastasis." (PMID 33292278, 2020). "In addition, ECM1 promoted aggressive phenotype of breast cancer by recruitment of MSN to promote its activation for invadopodia formation, which was closely correlated with breast cancer invasion." (PMID 31335317, 2019). "Additionally, ceramide regulates actin cytoskeleton dynamics in breast cancer cells through modulation of ezrin, radixin, moesin function." (PMID 24872355, 2014). "The aim of this study was to examine the expression of ERM (ezrin, moesin) and Rho (RhoA, RhoB and Cdc42) proteins in breast cancer (BC) patients and to investigate the relationship between the sub-cellular localisation of these proteins and clinicopathological characteristics and patient survival." (PMID 23420497, 2013).
breast carcinoma (continued). "Notwithstanding, evidence on the link between moesin and clinical feature of cancer is limited, while more clinical trials focus on the role of ezrin in different types of cancer progression, including in breast cancer." (PMID 21818323, 2011). "Taken together, our findings show that P, MPA, DRSP and NES alone or in combination with E2 increase breast cancer cell migration and invasion through the functional modulation of the actin-binding protein moesin and the induction of dynamic rearrangements of the actin cytoskeleton." (PMID 18541028, 2008). "In T47-D breast cancer cells, the activation of moesin was related to the concentration of E2 and was triggered by physiological amounts of the steroid, whereas in MDA-MB-468 cells no change in moesin phosphorylation was detected throughout the range of estradiol concentrations." (PMID 18493596, 2008). "In this manuscript we investigate the differential effects of natural progesterone and of the synthetic progestins MPA, DRSP and NES, alone or in combination with E2, on moesin activation, actin remodeling, cell migration and invasion in T47-D breast cancer cells." (PMID 18541028, 2008). "Interestingly, the expression of moesin was downregulated in breast cancers." (PMID 39457653, 2024). "Therefore, limiting Moesin expression level in breast cancer could be beneficial for the management of cancer progression." (PMID 37736741, 2023). "In these experiments, we detected a significant 40% decrease in the mammary tumor volume upon ebselen oxide administration that was perfectly correlated with tumor weight and similar to what we described with zuclopenthixol, another moesin‐mimicking compound we identified." (PMID 36912768, 2023). "However, there are still something interesting, a study in breast cancer indicated that the phosphorylation of moesin was necessary for programmed cell death-Ligand 1 (PD-L1) to stabilize on the cell membrane surface and silencing moesin can promote T cell activation in vitro and in vivo." (PMID 33838692, 2021). "Interestingly, gene silencing of moesin has been reported to remarkably decrease the plasma membrane localization of PD-L1 in human breast cancer, indicating a novel regulatory mechanism by which moesin modulates the protein expression levels of PD-L1 via post-translational modification." (PMID 34577118, 2021). "Additionally, miR-200b and miR-200c could suppress migration and invasion of breast cancer cells by regulating ezrin-radixin-moesin and fucosyltransferase-4." (PMID 31488193, 2019). "Thus, it cannot be excluded that also moesin might have a function in the regulation of ErbB receptor levels in other breast cancer cell lines or tissues." (PMID 27029001, 2016). "Thus, cytoskeletal rearrangement induced by estrogen through moesin may contribute to the development of estrogen-sensitive breast cancers, along with the enhanced metastatic behavior of such neoplasms in the presence of sex steroid hormones." (PMID 24904530, 2014). "In this study, we investigated the expression of the ERM (ezrin, moesin) and Rho (RhoA, RhoB, Cdc42) protein families in a homogeneous group of patients with stage II invasive ductal breast cancer (BC)." (PMID 23420497, 2013). "Previous studies have shown that LH/FSH signaling through LHR/FSHR activates G protein-coupled ROCK–moesin and FAK–paxillin axes, significantly enhancing invasive pseudopod formation and transendothelial migration in breast cancer cells." (PMID 40431589, 2025). "BRCA1 has previously been reported to interact with MSN/RDX through its BRCT domain, an interaction that localises the protein to the leading edges and focal adhesion sites in breast cancer cells." (PMID 39009827, 2024). "Further, we observed a good converse correlation in the expression levels of Moesin and FBXW2 among the cell lines and breast cancer patients." (PMID 37736741, 2023).
breast carcinoma (continued). "To further validate this regulatory axis in breast cancer, we assessed the correlation among the expression levels of these four proteins (FBXW2, pAKT, Moesin and SKP2) in HR positive breast cancer patients." (PMID 37736741, 2023). "Radixin was expressed in most of the breast cancer cell lines, while moesin was only detected in MDA-MB-231 and MDA-MB-468 breast cancer cells, as well as MCF10A cells." (PMID 36923551, 2022). "In response to the application of recombinant Hsp90ab1 and MSN, we observed a reduction in the EdU-based proliferation and transwell invasion of EO771 mammary tumor cells." (PMID 34976221, 2022). "To further study the relationship between MSN and immune response, we analyzed MSN and GZMB expression in breast cancer samples from The Cancer Genome Atlas database." (PMID 32941674, 2020). "Mesenchymal markers, such as vimentin, moesin, and receptor tyrosine kinase Axl, are highly expressed in TNBC basal B subtype of breast cancer cells, and vimentin and Axl proteins were expressed in a subset of human TNBC tumors from patients." (PMID 30777098, 2019). "Our previous studies in Dx-EVs showed a selective packaging of Ezrin, Radixin, Moesin and CD44 in resistant breast cancer cell-derived EVs." (PMID 26938523, 2016). "We used siRNA silencing of Ezrin, Radixin, Moesin and CD44 to evaluate the role of each protein in regulating P-gp function in drug-resistant breast cancer cells." (PMID 26938523, 2016). "Moesin and FAK are overexpressed in breast cancer, and their level of expression is related to the metastatic potential." (PMID 26733941, 2015). "Analysis of differential expression levels highlighted CLDND1, PLEKHA2, ACSL3, SLC30A9, MSN, CALM3 and PRKAR1A as potential regulators of breast cancer cell survival since they were affected by PKCδ siRNA in all cell lines." (PMID 26083392, 2015). "For instance, miR-200 was shown to target cytoskeleton remodeling proteins in breast cancer cells, including WASF3, Moesin, FHOD1, PPM1F, WIPF1 and Cofilin2, functional mediators of miR-200 in the suppression of invasion and/or metastasis." (PMID 26334393, 2015). "Between the many protein kinases controlled by c-Src in breast cancer cells, the ERM family member moesin is a key mediator of cytoskeletal and cell membrane remodeling." (PMID 26733941, 2015). "To this aim, we studied the consequences of RA treatment on the expression of moesin, c-Src and FAK and actin remodelling in breast cancer cells." (PMID 24720764, 2014). "Thus, the cytoskeletal rearrangement induced by estrogen through moesin may in part explain the carcinogenic actions of this steroid in estrogen-sensitive breast cancers, along with the enhanced metastatic behavior of such neoplasms in the presence of sex steroid hormones." (PMID 18493596, 2008). "On the other hand, irrespective of hormone expression status, Moesin is known to be involved in breast cancer progression and metastasis and is highly expressed in breast cancer." (PMID 37736741, 2023). "Since Moesin is a well-established oncogene and FBXW2 is a putative tumor suppressor, we sought to determine whether FBXW2 regulates breast cancer progression through controlling the expression level of Moesin." (PMID 37736741, 2023). "Literature shows a controversy between moesin (MSN) expression and prognosis in breast cancer." (PMID 34900662, 2021). "In contrast to HeLa cells, SKBR3 cells showed no expression of moesin, and we therefore focused on the presumed role of ezrin and radixin in the regulation of ErbB2 receptors in this breast cancer cell line." (PMID 27029001, 2016). "In line with this, moesin has been shown to be expressed in only 16% of all invasive ductal carcinoma and it is completely absent in several other breast cancer subtypes." (PMID 27029001, 2016). "ERM proteins show tissue- and cell-specific expression patterns and in contrast to many other cell lines, SKBR3 breast cancer cells do not express moesin." (PMID 27029001, 2016).
breast carcinoma (continued). "Overexpression and functional activation of FAK, moesin, and c-SRC in breast cancer cells may in part explain this epidemiologic finding." (PMID 26733941, 2015). "We found that neither the luminal A breast cancer cell line (MCF7) or the type 1 endometrial cancer cell line (Ishikawa) express FN1 or MSN, consistent with their pre-EMT phenotype, indicated by expression of E-cadherin and lack of ZEB1." (PMID 21501518, 2011). "Breast cancer cells transfected with constitutively active constructs showed an over-active moesin phosphorylation that was independent of estradiol." (PMID 18493596, 2008). "Supporting the requirement of PR, the same PR agonists did not alter moesin phosphorylation in MDA-MB-231 breast cancer cells, that do not express PR." (PMID 18665217, 2008). "Based on our results, it may be hypothesized that some of the effects of PRL on breast cancer cell motility may be triggered through recruitment of the small adapter protein, c-Src, and to FAK and moesin recruitment, followed by actin rearrangement and enhancement of cell motility." (PMID 26733941, 2015). "Therefore, we hypothesize that RA reduces moesin, FAK and c-Src expressions in breast carcinoma MCF7 cell lines by RARβ." (PMID 24720764, 2014). "In estrogen-receptor negative MDA-MB-468 breast cancer cells moesin was constitutively phosphorylated and exposure to estradiol did not alter this activation any further, suggesting that this protein may be basally over-active in these cells." (PMID 18493596, 2008). "We found that breast cancer patients with high FBXW2/low Moesin levels have significantly better RFS compared to those with low FBXW2/high Moesin, suggesting that the expression levels of both FBXW2 and Moesin could be used as prognostic biomarkers in breast cancer." (PMID 37736741, 2023). "In turn, SKP2 stabilizes Moesin by directing its non-degradable form of polyubiquitination and therefore AKT-Moesin-SKP2 oncogenic axis plays crucial role in breast cancer progression." (PMID 37736741, 2023). "Western Blot analysis confirmed the presence of the 68 kDa MSN protein in the Toledo NHL B-cell line (positive control) and absence of MSN in the MCF-7 breast cancer cell line (negative control)." (PMID 29556235, 2018). "ER- breast cancers, such as MDA-MB-468 cells, are not sensitive to estrogen administration in terms of moesin activation and cell migration." (PMID 18493596, 2008). "In addition, NONO, a nuclear protein, could interact with MSN to phosphorylate CREB and upregulate downstream gene expression as well as promote the progression of breast cancer." (PMID 34993131, 2021). "A similar result is found for breast cancer invasion of three-dimensional matrices, where the inhibition of G proteins, ROCK and MAPK all result in a significant decrease of progesterone-induced cell invasion, notwithstanding the fact that MAPK are not required for moesin activation by progesterone." (PMID 18665217, 2008).
glioma (18 papers, 2013 to 2025). A benign or malignant brain and spinal cord tumor that arises from glial cells (astrocytes, oligodendrocytes, ependymal cells). "MSN, an actin-binding protein, has been implicated in the cytoskeletal reorganization associated with cell shape and motility, facets central to glioma cell invasion, and interactions with the microenvironment." (PMID 38137116, 2023). "Of interest also, TNFAIP6 was identified among ARL4C and MSN as a neural progenitor cell-associated chemoradiotherapy resistance gene set for the prognosis of glioma." (PMID 37511403, 2023). "This study found that moesin (MSN) acts as a key promotor of chemoradiotherapy resistance in glioma stem cells (GSCs), enhancing their proliferation and stemness maintenance." (PMID 39921260, 2025). "Overexpression of miR-200c negatively regulates Moesin expression to inhibit the proliferation and invasion of glioma cells, Moesin is highly expressed in glioma specimens, and Moesin promotes glioma cell development." (PMID 37740172, 2023). "Four glioma antigens, namely ANXA5, FKBP10, MSN, and PYGL, associated with superior prognoses and infiltration of APCs were selected." (PMID 34512630, 2021). "The differentially expressed and mutational profile of glioma was constructed, and four targetable antigens (ANXA5, FKBP10, MSN, and PYGL) were further confirmed." (PMID 34512630, 2021). "Glioma progression involves the interaction of phospho-moesin with CD44 and the Wnt-β-catenin pathway." (PMID 33312163, 2020). "Other reports suggested that the expression of Moesin in glioma cells was significantly higher than that in normal astrocytes and there was a strong negative correlation with progression-free survival and overall survival." (PMID 33292278, 2020). "For example, In glioma, miR-200c represses tumor growth and metastasis via interaction with moesin (MSN) mRNA." (PMID 29471827, 2018). "This prompted us to further investigate the role of moesin in HA-induced cell migration in gliomas in the context of CD44-HA interaction." (PMID 23855374, 2013). "This clearly demonstrated an important role of moesin downstream of HA-CD44 interaction in glioma cells." (PMID 23855374, 2013). "Twelve of 15 GBM samples showed strong moesin expression on the membrane of glioma cells, while eight of 15 cases showed strong membranous CD44 expression." (PMID 23855374, 2013). "Using co-immunoprecipitation assays, we further demonstrated that moesin interacts with CD44 in glioma cells only after treatment with HA; this implicates a novel role of moesin in HA-CD44 signaling in gliomas." (PMID 23855374, 2013). "Our results demonstrated overexpression of both CD44 and moesin in both glioma cell lines as compared to NHA." (PMID 23855374, 2013). "Both GBM tissues and glioma cell lines (U87 / U373) demonstrated membranous expression of moesin and CD44, as revealed by immunohistochemistry and immunofluorescence, respectively." (PMID 23855374, 2013). "Our IHC results revealed an exclusive strong membranous expression of both CD44 and moesin in glioma cells in paraffin-embedded sections of GBM tissues." (PMID 23855374, 2013). "Both glioma cell lines (U87 and U373) transfected with siRNA targeting moesin, resulting in its reduced expression, demonstrated significantly lower migration from the upper chamber to the lower chamber as compared to no transfection controls." (PMID 23855374, 2013). "We found that MSN was highly expressed in high‐grade glioma cells (both GBM and GS)." (PMID 39921260, 2025). "In the intricate landscape of glioma pathogenesis, the elucidation of risk scores derived from pivotal hub genes—RPL3, RPL12, PTEN, IFNGR2, KLF10, PLAUR, MSN, and IKBIP—emerged as a critical component in understanding the disease’s progression and patient stratification." (PMID 38137116, 2023).